MMP1 (matrix metallopeptidase 1)
Diseases named in the same sentence as MMP1 in open-access papers (continued):
Sharing a sentence is not in itself a finding about the gene and the disease.
keratoconus (15 papers, 2010 to 2025). A degenerative, structural disorder of the eye, characterized by a cone-shaped protrusion of the cornea. "In fact, proinflammatory cytokines (IL-1, IL-6, TNF-α, and TGF-β), oxidative stress, or degradation of collagens by metalloproteases (MMP-1, MMP-3, and MMP-9) has been implicated in keratoconus pathophysiology." (PMID 35075374, 2022). "On the other hand, they revealed a significant increase in matrix metalloproteinase-one (MMP-1) in the keratoconus group." (PMID 30245588, 2018). "Using a nano-LC tandem mass spectrometry approach, tears of 44 keratoconus patients were compared with 20 healthy controls that identified the elevation of cytokeratins, matrix metalloproteinase 1 (MMP1) and mammoglobin B (SGB2A1)." (PMID 27493978, 2016). "The differential expression of tear film proteins such as MMP-1, keratins, and mammaglobin B can be found in keratoconus subjects." (PMID 21031023, 2010). "Our study may be one of the first to show the presence of MMP-1 in the tears of keratoconus subjects." (PMID 21031023, 2010). "Interestingly, NicheNet predicted that ImC-derived IL24 may induce the differential expression of MMP1 in keratoconus CSCs." (PMID 35821117, 2022). "Furthermore, an increased in tear matrix metalloproteinases (e.g., MMP-1 and MMP-13) and inflammatory mediators following eye rubbing has been observed in patients with keratoconus, which may be associated with the progression of keratoconus." (PMID 40606911, 2025). "Further cyclical mechanical experiments revealed that several protease genes (including MMP1, MMP3, CTSD and CTSK) can be induced by stretch, indicating the inductive role of mechanical stretch in keratoconus pathogenesis." (PMID 35821117, 2022). "Partly in line with these results, increased tear levels of MMP-1, MMP-3, MMP-7, MMP-9, and MMP-13; IL-4, IL-5, IL-6, and IL-8, and TNF-α, -β were found in keratoconus." (PMID 26881061, 2016). "The study showed increased levels of gelatinases and collagenases (1.9 times higher), as well as elevated MMPs, cytokines (MMP-1, MMP-3, MMP-7, MMP-13, and IL-6), and TNF-alpha and TNF-beta in the keratoconus group compared with the normal group." (PMID 27563164, 2016). "Further cyclical mechanical experiments on human corneal stromal cell lines demonstrated that mechanical stretch prompted the expression of several protease genes, including MMP1, MMP3, CTSD and CTSK, implying the activating effect of mechanical stretch on proteases during keratoconus progression." (PMID 35821117, 2022). "Albeit, recent studies have shown that matrix metalloproteinases MMP1 and 9, AZGP1, SFRP1, IGKC and cell adhesion molecules ICAM-1 and VCAM-1 to be specifically regulated in keratoconus, indicating their probable exclusive role in keratoconus." (PMID 27493978, 2016). "Increased expression of matrix metalloproteinase-1 (MMP-1) was found in keratoconus subjects with and without gas permeable contact lenses (p=0.02)." (PMID 21031023, 2010).
esophageal squamous cell carcinoma (14 papers, 2010 to 2022). Esophageal squamous cell carcinoma (ESCC) is a type of esophageal carcinoma (EC) that can affect any part of the esophagus, but is usually located in the upper or middle third. "In esophageal squamous cell cancer, MMP1 was expressed higher in tumor tissues than their adjacent normal tissues." (PMID 35426219, 2022). "Myo1b is also overexpressed in Esophageal Squamous Cell Carcinoma (ESCC) clinical samples, in this cancer Myo1b is associated with cancer cell aggressiveness and metastasis, downstream genes controlled by Myo1b includes MMP1/13 both of which are highly expressed in ESCC clinical specimens." (PMID 34974807, 2022). "The overexpression of MMP1 and MMP12 have been associated with the development of tumors in other anatomical regions, including esophageal SCC and head and neck SCC (HNSCC)." (PMID 34638231, 2021). "MMP1 promoted cell proliferation and migration of esophageal squamous cell carcinoma." (PMID 34249502, 2021). "Another published research showed that the level of MIR31HG in esophageal squamous cell carcinoma (ESCC) tissues was positively correlated with the expression of furin and matrix metalloproteinase 1 (MMP1)." (PMID 33334367, 2020). "In esophageal squamous cell carcinoma (ESCC) and HNSCC, decreased MMP1 inhibited tumor invasion and metastasis in vitro and vivo." (PMID 36105241, 2022). "Additionally, the findings of elevated gene and protein expression of MMP-1 by BE and EAC as preinvasive factor might also be important for esophageal squamous-cell carcinomas, although it was only investigated in a smaller sample." (PMID 20946664, 2010).
head and neck cancer (14 papers, 2009 to 2024). A primary or metastatic malignant neoplasm affecting the head and neck. "An inverse correlation between MMP1 expression and cancer prognosis has been reported in many cancers and the rs1799750 variant has been linked with an increased risk of developing lung, ovarian, colorectal, and head and neck cancers." (PMID 19551141, 2009). "For head and neck cancers, MMP-1, MMP-2, MMP-9 and membrane type-1 MMP were constantly observed overexpressed in the tumor tissues and were considered associated with the development and progression of cancer." (PMID 28427180, 2017). "For head and neck cancers, MMP-1, MMP-2, MMP-9 and membrane type-1 MMP have been found overexpressed in the tumor tissues and been associated with cancer progression." (PMID 25423087, 2014). "MMP1 is an important member of the MMP endopeptidase family that plays a critical role in the development of head and neck cancer (HNC)." (PMID 23441173, 2013). "Disease-free survival was analyzed on head and neck cancer samples from The Cancer Genome Atlas (TCGA), and the results revealed that patients with higher MMP1 expression exhibited significantly poorer survival than those with lower MMP1 expression (p = 0.017)." (PMID 35444950, 2022). "Because NPC-BM1 expresses more MMP-1 than other head and neck cancers, MMP-1 may contribute to the unique high metastatic rate of NPC-BM1." (PMID 28672814, 2017). "Among the SASP factors we investigated in the current study, in addition to MMP1 and MMP3, overexpression of MMP10 has been reported to promote invasion, metastasis in head and neck cancer, and tongue cancer." (PMID 39756915, 2024). "Microarray analysis reveals that MMP1 and MMP2 are the most significantly upregulated genes in NPC biopsies, compared with lymphohyperplasia, adenoid tissues, and head and neck cancer." (PMID 24955581, 2014).
heart failure (14 papers, 2007 to 2025). Inability of the heart to pump blood at an adequate rate to meet tissue metabolic requirements. "Here, DNER is a potential protective factor against heart failure, while MMP-1 and CD6 are potential risk factors." (PMID 39726944, 2024). "In contrast, it is described that the 2G polymorphism is related to higher transcription rates of MMP-1 in fibroblasts, which was shown to lead to substantially reduced heart failure-related mortality." (PMID 37160529, 2023). "However, in heart failure patients, an ischemic etiology with previous MI and regional LV dysfunction was more frequent in MMP-1 2G allele carriers in the same study." (PMID 37160529, 2023). "We discovered that 7 out of these 91 inflammatory factors influence heart failure, with 4 showing a significant causal relationship (CXCL9, IFN-γ, LIFR, UPA) and 3 being potentially related influencing factors (DNER, MMP-1, CD6)." (PMID 39726944, 2024). "Three inflammatory factors had a potential causal relationship with heart failure, with DNER as a potential protective factor, and MMP-1 and CD6 as potential promotive factors." (PMID 39726944, 2024). "In addition, our Mendelian randomization also identified potential causative inflammatory markers such as MMP-1 and T-CD6, which may promote the onset of heart failure, and DNER, which may alleviate it." (PMID 39726944, 2024). "Among the secreted MMP members, we selected collagenase MMP-1 and gelatinase MMP-2, which are up-regulated in abnormal arteries and in heart-failure patients, respectively." (PMID 26495844, 2015). "During the initial 12 hours post-fibrinolysis, increased MMP-1 activity due to inadequate TIMP-1 inhibition may contribute to adverse outcomes, including more frequent heart failure symptoms observed in patients with a lysis-PCI interval of ≤9.6 hours." (PMID 39877021, 2024).
metastatic tumors (14 papers, 2010 to 2023). "MMP-1 knockdown resulted in lower levels of MMP-1 expression in the metastatic tumors, as assessed by immunohistochemistry." (PMID 23696795, 2013). "PEA3 subfamily members are upregulated in human adenocarcinomas and expression correlates with MMP-1 expression and late stage metastatic disease." (PMID 21143918, 2010). "We further studied the EV-derived mRNA expression of TIMP-1, TIMP-2 and MMP-1 mRNAs in plasma EVs from two groups of ccRCC patients: patients with localized disease before and after tumor removal surgery (Group A) and patients with metastatic disease (Group B)." (PMID 32610589, 2020). "The highest differentially expressed genes in metastatic (MET and PRI+) versus non-metastatic tumors (PRI-) and SES included PLAU, PLAUR, MMP1, MMP10, MMP13, ITGA5, VEGFA, and various inflammatory cytokine genes." (PMID 35480116, 2022). "The highest signal was from MMP-3 like it does in the metastatic tumors (mean IOD 28,600), followed by MMP-1 (mean IOD 20,200), MMP-9 (mean IOD 13,200), and TIMP-1 (mean IOD 12,300)." (PMID 27975070, 2016). "MMP1 is overexpressed during lymph node metastasis in xenografted mice in a TNBC model and exosomes extracted from the serum of metastatic TNBC patients displayed higher levels of MMP1 than in patients with no metastatic disease." (PMID 38017545, 2023). "MMP-1 expression was not correlated with any markers in the primary and the metastatic tumor tissues." (PMID 25945089, 2015). "Given that MMPs are key proteins involved in the metastatic process, in the present study we evaluated the role of Pit-1 on the expression and biological activity of two collagenases, MMP-1 and MMP-13, whose role in several processes of the metastatic disease is well known." (PMID 25527274, 2014). "Evaluation of expression of MMP-1, MMP-3, MMP-9, and TIMP-1 in 54 samples from patients with no metastatic tumors in lymph nodes was indirectly estimated by obtaining numeric values of intensity IOD, from the corresponding immunohistochemistry results (standard process)." (PMID 27975070, 2016).
Myocardial fibrosis (14 papers, 2013 to 2025). "Astragaloside treatment downregulates interstitial collagenase (encoded by MMP1) expression and attenuates the myocardial fibrosis and reduces the mortality in mice with chronic myocarditis." (PMID 34456633, 2021). "Although MMPs have been associated with myocardial fibrosis, MMP1 has been reported to attenuate the development of cardiac fibrosis in mouse models, however other studies reported the increase of circulating MMP1 levels in HCM patients." (PMID 40843168, 2025). "In a previous study, they also showed that CsA caused intense myocardial fibrosis and the increase in MMP-2, while MMP-1 and MMP-9 levels were unchanged." (PMID 35681984, 2022). "Recently, a novel laboratory parameter measuring irreversible myocardial fibrosis by the ratio of serum carboxy-terminal telopeptide of collagen type I to serum matrix metalloproteinase-1 (CITP:MMP1) has been introduced." (PMID 35897100, 2022). "In the process of myocardial fibrosis induced by pressure load, a decrease in MMP-1 expression can prevent ventricular expansion, protect heart function, and increase the myocardial MMP 1/TIMP-1 ratio, which is an effective strategy to prevent hypertensive heart disease." (PMID 25861361, 2015). "In addition to inhibiting myocardial fibrosis through TGF-β1/Smad2 signaling pathway, icariin can also inhibit myocardial fibrosis and delay the progression of HF by regulating the protein expression of α-smooth muscle actin (α-SMA) and MMPs/MMP-1." (PMID 38444481, 2024). "Moreover, it has been reported that increased matrix metalloproteinase-1 (MMP-1) turnover lead to reduced collagen I and III degradation and development of subendocardial myocardial fibrosis." (PMID 33950321, 2021).
Granuloma (13 papers, 2010 to 2026). A compact, organized collection of mature mononuclear phagocytes, which may be but is not necessarily accompanied by accessory features such as necrosis. "This increased expression of MMP-1 and -3 were associated with microglia in the granuloma and peri-granuloma region and p38-positive microglia infiltrating necrotizing CNS-TB granulomas." (PMID 35095865, 2021). "The primary pathological difference was loss of collagen within the MMP-1-expressing mouse granulomas." (PMID 30889803, 2019). "Dysregulation of matrix metalloproteinase 1 (MMP-1) has been recently implicated in granuloma activation through experimental studies, but the mechanism is not well understood." (PMID 34993126, 2017). "Monocytes produce MCP-1 and MMP-1 in response to M. tuberculosis antigens and their presence in M. tuberculosis-induced granulomas is a hallmark of TB infection." (PMID 20111728, 2010). "We also observed a significant increase in the imputed frequency of MMP1+CXCL5+ fibroblasts in TB LN granuloma compared with control LNs via deconvolution of bulk RNA-seq profiles." (PMID 41489684, 2026). "Previous studies have shown that MMP-1, -3, -7, -9, and -10 are upregulated in the sputum or granulomas from TB patients or macrophages infected with M. tb." (PMID 36992931, 2023). "TB granulomas (tuberculomas), which occur frequently in CNS-TB, demonstrate high expression of several MMPs including MMP-1, -2, -3 and -9." (PMID 35095865, 2021). "Most of studies pay close attention to collagen breakdown and alveolar destruction mediated by MMP-1 production from Mφs, and initiation of recruitment of new monocytes to develop granuloma mediated by MMP-9 production." (PMID 35095838, 2021). "Even microarray profiling has shown increased (660 fold) MMP-1 gene expression in human TB granulomas, cavity areas (rabbit model) and macaque lungs compared to healthy lungs." (PMID 32218787, 2020). "In human TB, several matrix metalloproteinases (MMPs), including MMP-1, -2, -8, -9, and -14, are markedly upregulated in expression in granulomas, and it was suggested that the upregulation of MMPs eventually leads to collagen destruction and granulomas necrosis (38, –, 42)." (PMID 35266819, 2022). "In addition to MMP-9, MMP-1 and -3 secretion were also found to be highly expressed in the center of granuloma which decrease towards the fibrotic, peri-granuloma region." (PMID 35095865, 2021). "Moreover, the functional importance of MMP-1 in Tb-related tissue destruction was suggested by a study with human MMP-1 transgenic mice showing increased collagen destruction in Tb granulomas." (PMID 27455234, 2016). "This support the notion that increased production of MMP-1 may destabilize the organization of new granulomas, thus contributing to the dissemination of infected cells and disease progression." (PMID 20111728, 2010). "As granulomas in TB prevent the spread of infection, MMP-1 may contribute to the dissemination of infection and to disease progression." (PMID 20111728, 2010). "In brain biopsies from patients with CNS TB, MMP-1 secretion was highest in the granuloma, and elevated concentrations of MMP-1 and -3 were associated with microglia in the peri-granuloma region and surrounding brain parenchyma and p38 positive microglia infiltrating necrotizing TB granulomas." (PMID 30889803, 2019). "Moreover, mice do not express MMP-1, which, along with other MMPs, is associated with tissue destruction and transmission in disseminated human granuloma." (PMID 29698476, 2018). "MMP1+CXCL5+ fibroblast, however, showed the largest difference for marker expression between the Visium spots on the granuloma cuff and those inside/outside the cuff." (PMID 41489684, 2026). "Among them, MMP-1 and MMP-9 are most extensively studied owing to their roles in the creation of the granuloma and destruction of lung tissue." (PMID 35095838, 2021).
Granuloma (continued). "Cells producing large amounts of MMP-1 and MCP-1 were mainly located in areas surrounding old granulomas." (PMID 20111728, 2010). "In particular, the MMP1+CXCL5+ fibroblast subset, expressing a myofibroblast-like gene signature, was associated with severe disease and higher bacterial burden in nonhuman primate granulomas." (PMID 41489684, 2026).
Stroke (13 papers, 2012 to 2025). Sudden impairment of blood flow to a part of the brain due to occlusion or rupture of an artery to the brain. "It has been reported that the expression of MMP1 in patients with acute stroke is significantly increased and MMP1 polymorphism is a potential marker for predicting stroke." (PMID 35153756, 2021). "In this study, subjects carrying the allele associated with lower MMP1 expression exhibited increased left carotid intima-media thickness, and this finding is presumed to increase the risk of stroke among elderly outpatients." (PMID 30034880, 2018). "MMP1 (matrix metallopeptidase 1) belongs to a family of protein-digesting enzymes that degrades the extracellular matrix in both physiological and pathological conditions including stroke." (PMID 23874591, 2013). "Similar to CHD and HF, higher concentrations of GDF15 and IL6, along with TNFR1, Eotaxin, MMP1, and MMP2, conferred the highest HRs for incident stroke." (PMID 39695064, 2025). "The AUCs for lipocalin-2, sP-selectin, glial cell-derived neurotrophic factor (GDNF), sVCAM-1, sRAGE, MMP-7, D-dimer, MMP-1, Apolipoprotein CIII, myoglobin and BNDF were ≥0.75 in predicting stroke amongst children with TBM." (PMID 33930055, 2021). "Additional studies examining the role of MMP-1 and MMP-8, and other MMPs in stroke are clearly warranted." (PMID 23565108, 2013). "The role of other MMPs in stroke are not well described although it also known that MMP-1 (collagenase-1) and MMP-8 (neutrophil collagenase or collagenase-2) are upregulated in the infarcted tissue in human brain compared to healthy control areas." (PMID 23565108, 2013). "Indeed, MMP-1 and MMP-2 appear to initiate the damage cascade early during the acute rt-PA thrombolysis phase within 2–6 h (median 3.8 h) after ischemic brain injury, and periods of enhanced BBB permeability are present at 4–8 h and again at 12–16 h after stroke onset." (PMID 30186167, 2018). "sVCAM1, MMP-1, sRAGE, CXCL10 are higher in TBM patients with stroke compared with those without stroke, and other forms of meningitis in children." (PMID 38264653, 2023). "In contrast, we observed low levels of MMP-1 and sVCAM-1 in CSF patients with TBM stroke compared to the no-stroke group." (PMID 33930055, 2021).